MUC4 (mucin 4, cell surface associated)
Diseases named in the same sentence as MUC4 in open-access papers (continued):
Sharing a sentence is not in itself a finding about the gene and the disease.
gastric cancer (continued). "Both MAb 8G7 and MAb 1G8 react with human gastric cancer tissues, although the locations of MUC4/8G7 and MUC4/1G8 expression showed a marked difference." (PMID 23152882, 2012). "In gastric cancer tissues, MUC4/8G7 was expressed mainly in the cytoplasm of the neoplastic cells of pap and tub, whereas MUC4/1G8 was expressed mainly at the cell apexes of pap and tub or intracytoplasmic mucin substance of sig." (PMID 23152882, 2012). "Other studies have shown that in SRCC type gastric cancer cells, MUC4 is required for the activation of ErbB2." (PMID 18781152, 2008). "The number of MUC4 overexpressing AGS gastric cancer cells (AGS-MUC4) migrated to the lower surface of the porous membrane was significantly high (P<0.005) than that of the vector control (AGS-vector) cells." (PMID 18781152, 2008). "In this study, we showed that MUC4 is overexpressed in gastric cancer tissues as compared with normal adjacent tissues." (PMID 18781152, 2008). "MUC4 showed a significant overexpression in gastric cancer tissues compared with the normal adjacent tissues." (PMID 18781152, 2008). "As a first step toward studying the role of MUC4 in gastric cancer, we did immunohistochemical analysis of MUC4 expression on TMA samples of gastric adenocarcinoma and normal adjacent area." (PMID 18781152, 2008). "In contrast to MUC4, mutated MUC16 may serve as a prognostic marker for favorable survival outcomes in gastric cancer." (PMID 39338204, 2024). "Most patients with metaplasia do not progress to cancer, but MUC4 expression was strongly linked with Ki-67 expression in gastric cancer tissues in our human cohort." (PMID 37674528, 2023). "Besides, the combined mutation status of MUC4, MUC16, and TTN showed the potential to predict TMB and immunotherapy efficacy in gastric cancer and pan cancer." (PMID 37814942, 2023). "Thus, we used a tissue microarray (TMA) to assess MUC4 expression in samples from 47 recent gastric cancer cases seen at medical centers in the U.S. Pacific Northwest." (PMID 37674528, 2023). "A recent study indicated a strong expression of the MUC4 gene in human gastric cancers." (PMID 34394838, 2021). "In addition, catecholamine-induced β2-AR activation mediates desensitization of gastric cancer cells to EGFR antibodies (transtuzumab) by upregulating Mucin 4 (MUC4) expression." (PMID 33142779, 2020). "Representative immunohistochemical results of 5 participants in family No. 14 which showed complete cosegregation with MUC4 variants (rs774527434) and contained the largest number of gastric cancer patients are shown." (PMID 32701958, 2020). "Since MUC4 was closely related to gastric cancer, it may be possible to suppress gastric cancer by regulating MUC4 expression." (PMID 31915505, 2019). "To identify the expression of MUC4 in human gastric cancer and normal gastric tissues, we performed immunohistochemistry staining on normal gastric samples located away from cancer (n = 240) and gastric cancer (n = 240), respectively." (PMID 31915505, 2019). "The expression of MUC4 in human gastric cancer tissues was assayed by immunohistochemistry." (PMID 31915505, 2019). "We found that the MUC4 gene was strongly expressed in human gastric cancer tissues." (PMID 31915505, 2019). "Taken together, ALA inhibits TNF-α-induced MUC4 in gastric cancer cells." (PMID 31915505, 2019). "We found that MUC4 was upregulated in gastric cancer compared to normal tissues." (PMID 31915505, 2019). "Furthermore, to explore the role of STAT3 in the inhibition of MUC4 by ALA in gastric cancer cells, AGS, BGC-823, and MKN-28 cells were incubated with 0, 0.5, 1, or 2 mM ALA for 24 h in RPMI with 10% FBS when cell confluence was 60%." (PMID 31915505, 2019).
gastric cancer (continued). "Among them, MUC16 and MUC20 membrane-bound mucins and their combination MUC4/MUC16/MUC20 is associated with a poorer overall survival in different cancers including pancreatic, colon and stomach cancers suggesting MUC4/MUC16/MUC20 as a poor prognostic signature for these cancers." (PMID 30236127, 2018). "In other organs, the MUC4/MUC16/MUC20high group was associated with an increased hazard ratio and reduced overall survival in bladder cancer, colon cancer, lung adenocarcinoma, lung squamous adenocarcinoma, skin cancer, stomach cancer." (PMID 30236127, 2018). "The MUC4 mRNA was detected in the two gastric cancer cell lines." (PMID 23152882, 2012). "The high expression of MUC4 in the well differentiated adenocarcinoma also may affect the survival of patients with gastric cancer." (PMID 23152882, 2012). "Thus, a special attention was paid to the comparison of two anti-MUC4 MAbs by Western blotting and IHC of two gastric cancer cell lines, before the IHC study of human gastric cancer tissues." (PMID 23152882, 2012). "In the present study, we examined the expression profiles of MUC4 as well as MUC1 in early gastric cancer tissues, and found that MUC4 and MUC1 expression in the early gastric cancers would become poor prognostic factors by lymph vessel invasion, blood vessel invasion and lymph node metastasis." (PMID 23152882, 2012). "Unfortunatly, there are few studies of the MUC4 expression profile in human gastric cancer." (PMID 23152882, 2012). "Our study also indicates that MUC4 can be targeted for treatment of gastric cancer." (PMID 18781152, 2008). "Hence, our study provides for the first time, the importance of MUC4 in gastric cancer and explains the possible mechanism through which MUC4 can promote aggressive property of poorly differentiated gastric non-SRCC cells." (PMID 18781152, 2008). "Therefore, overexpression of MUC4 in adult gastric carcinoma supports the concept of ‘fetal antigen’ expression during malignant condition and indicates its possible role in gastric cancer progression." (PMID 18781152, 2008). "In this study, we examined and compared the expression of MUC4 in gastric cancer tissues." (PMID 18781152, 2008). "On the basis of these earlier observations, we wanted to determine whether MUC4 exerts its function through regulating ErbB2 expression and activation in AGS-MUC4 gastric cancer cells." (PMID 18781152, 2008). "Finally, we confirmed in our TMA that in human subjects with gastric cancer, pit cells (expressing MUC5Ac) could express MUC4." (PMID 37674528, 2023). "Immunohistochemistry indicated that MUC4 was downregulated in the noncancerous gastric mucosa of subjects with MUC4 germline missense variants, suggesting that loss of the protective function of MUC4 predisposes an individual to gastric cancer." (PMID 32701958, 2020). "We sought to determine whether ALA can suppress TNF-α-induced MUC4 in human gastric cancer; to this end, we pretreated AGS, BGC-823, and MKN-28 cells with the indicated concentrations of ALA for 24 h followed by exposure of the cells with 20 ng/mL TNF-α for 4 h." (PMID 31915505, 2019). "Its inhibitory effect on gastric cancer cells may be related to the inhibition of MUC4 expression." (PMID 31915505, 2019). "Also, we could not investigate the association of MUC4 variants with disease severity as some of the patients with gastric cancer were treated at other hospitals and clinical data about disease severity like tumor staging and survival were not available." (PMID 32701958, 2020). "Mucin 4 (MUC4) is membrane-bound mucin, which is expressed in normal gastric mucosa and gastric cancer." (PMID 31915505, 2019). "We propose the MUC4/MUC16/MUC20high signature as a marker of poor prognostic for pancreatic, colon and stomach cancers." (PMID 30236127, 2018).
gastric cancer (continued). "The examination of MUC4 and MUC1 expression in the gastric cancers would become a useful marker to predict poor prognostic factors related with vessel invasion, even in the early stage." (PMID 23152882, 2012). "Here, we have shown that MUC4 overexpression in poorly differentiated AGS, gastric cancer cells, increases its aggressive cancer property in both in vitro and in vivo experiments." (PMID 18781152, 2008). "In addition, we also proved that ALA inhibited gastric cancer cell invasion much strongly than anti-MUC4, which suggested that the inhibitory effect of ALA on gastric cancer was partly by suppression of MUC4." (PMID 31915505, 2019). "These experiments demonstrated that ALA inhibited both endogenous MUC4 and MUC4 induced by TNF-α in gastric cancer cells, which may contribute to its inhibition on gastric cancer." (PMID 31915505, 2019). "In the non-neoplastic mucosa of the cases with gastric cancer, MUC4/8G7 was expressed sometimes in the cytoplasm of surface mucous epithelium, and frequently but weakly in the cytoplasm of fundic and pyloric glands." (PMID 23152882, 2012). "Both MUC4 and MUC1 expression in the gastric cancers may be related with the poor prognostic factors, such as lymphatic invasion, venous invasion and lymph node metastasis, by means of different mechanism." (PMID 23152882, 2012). "Furthermore, the high incidence of tumours in animals injected with AGS-MUC4 cells than animals inoculated with AGS-vector cells, indicate the role of MUC4 in tumorigenicity of gastric cancer cells." (PMID 18781152, 2008). "In this study, we have shown that MUC4 is overexpressed in the gastric cancer and its expression pattern does not correlate with type, differentiation or stage of cancer." (PMID 18781152, 2008). "In addition, overexpression of MUC4 in AGS, gastric cancer cells, increases both total and phosphorylated form of ErbB2." (PMID 18781152, 2008). "It remains to be investigated whether all mucins (MUC1, MUC2, MUC4, MUC 5AC, MUC 5B, MUC6 etc.) may carry these sialylated and sulfated oligosaccharidic sidechains detected in intestinal metaplasia, gastric carcinoma and cholelithiasis." (PMID 17565665, 2007). "Also in the present study of the gastric cancers in the early stage, there was no siginificant correlation between expression of MUC4 and MUC1." (PMID 23152882, 2012). "However, to date there is a lack of knowledge about the functional significance of MUC4 in poorly differentiated gastric cancers other than the SRCC subtypes." (PMID 18781152, 2008). "This suggests that MUC4 itself may not be a potential marker for early diagnosis of gastric cancer." (PMID 18781152, 2008). "Thus, the IHC signal of MUC4/1G8 detected in the gastrectomy specimens may show a significant meaning of the epitope detected by MAb 1G8, although there was no reactivity of MUC4/1G8 expression in human gastric cancer cell lines (SNU-16 and NCI-N87)." (PMID 23152882, 2012). "Further, to check the actual role of MUC4 in non-SRCC type poorly differentiated gastric cancer cells, MUC4 was ectopically overexpressed in a gastric adenocarcinoma cell line (AGS), which has an undetectable expression level of MUC4." (PMID 18781152, 2008).
ovarian carcinoma (25 papers, 2008 to 2024). A malignant neoplasm originating from the surface ovarian epithelium. "In our recent study, we have shown a direct association of the MUC4 mucin with the metastatic human ovarian cancer phenotype and also provided experimental evidence for a functional role of MUC4 in altered growth behavioral properties of the tumor cell." (PMID 21521521, 2011). "Our studies demonstrate a direct association of the MUC4 mucin with increased motility in ovarian cancer cells." (PMID 18665193, 2008). "In conclusion, this work is the first report of the direct association of MUC4 with the motile phenotype in ovarian cancer cells." (PMID 18665193, 2008). "MUC4 is highly upregulated in pancreatic and ovarian cancers and is associated with poor prognosis." (PMID 32709695, 2020). "Our findings provide experimental support for the hypothesis that MUC4 mucin expression is associated with a higher metastatic potential and thereby a poor prognosis in ovarian cancer." (PMID 19014671, 2008). "Our findings provide experimental support for the hypothesis that MUC4 expression is associated with a higher metastatic potential and thereby a poor prognosis in ovarian cancer." (PMID 18665193, 2008). "Previous studies have associated differential MUC4 expression with a number of cancers, including pancreatic, lung, breast, gall bladder, salivary gland, prostate and ovarian cancer, indicating that MUC4 may be a good candidate as a diagnostic and prognostic marker." (PMID 24947164, 2014). "MUC4 is also overexpressed in ovarian cancer and promotes the pathobiology and aggressiveness of ovarian cancer cells." (PMID 34336844, 2021). "MUC4 expression is a marker of good prognosis in upper aerodigestive tract carcinomas, but a marker of poor prognosis in ovarian carcinomas." (PMID 27829225, 2017). "In completely metastatic ovarian cancer cells, aberrant expression of MUC4 implies mucins are correlated with the malignant transformation of cells during specific stages of metastatic progression." (PMID 27829225, 2017). "We and others have shown that HER2 interacts with MUC4 in pancreatic and ovarian cancer cells, and MUC4 knockdown results in decreased HER2 signaling and cell proliferation." (PMID 26035354, 2015). "In ovarian cancer cells, MUC4 overexpression upregulates Snail, focal adhesion kinase (FAK), Twist1/2, and MAPK signaling cascade proteins and downregulates E-cadherin and CK18 expression." (PMID 26356073, 2015). "Previous studies from our laboratory have indicated that MUC4 augments proliferation and motility of pancreatic and ovarian cancer cells." (PMID 23408941, 2013). "In the present study, we analyzed the expression of the HER2 protein in MUC4-transfected ovarian cancer cells." (PMID 21521521, 2011). "The exogenous MUC4 expression in ovarian cancer cells showed an increase in HER2 expression and colocalization, suggesting that MUC4 is involved in the stabilization of HER2 protein." (PMID 21521521, 2011). "In conclusion, overexpression of MUC4 induces the HER2 level and enrichment of cancer stem cells in MUC4-transfected ovarian cancer cells." (PMID 21521521, 2011). "One of the well known tumor antigens is the epithelial cell mucin MUC4, which is aberrantly expressed in ovarian cancer as compared to the normal ovary and plays a pivotal role in the aggressiveness and metastasis of ovarian cancer cells." (PMID 21521521, 2011). "This suggests that overexpression of MUC4 leads to enrichment of the SP population in ovarian cancer cells." (PMID 21521521, 2011). "Since MUC4 is an emerging target for ovarian cancer, our study provides a new direction from which to address the roles of MUC4 in the development of gynecological disorders." (PMID 21349170, 2011). "This further suggests that overexpression of MUC4 results in the enrichment of the cancer stem cell population in ovarian cancer cells." (PMID 21521521, 2011).
ovarian carcinoma (continued). "In this study, we have investigated increased expression of HER2 and the cancer stem cell population in MUC4 overexpressed ovarian cancer cells." (PMID 21521521, 2011). "Circular colonies isolated from MUC4 overexpressed ovarian cancer cells show an increased expression of cancer stem cell specific markers (ALDH1and CD133) and the self-renewal maker (Shh)." (PMID 21521521, 2011). "In the present study, we aimed to analyze the cancer stem cell population in MUC4 overexpressed ovarian cancer cells." (PMID 21521521, 2011). "Further, an interesting observation of tumor sphere like circular colony formation was observed predominantly in MUC4-transfected ovarian cancer cells and these colonies were isolated from the cells and analyzed with cancer stem cell markers." (PMID 21521521, 2011). "In future, this study would be helpful for MUC4-directed therapy for the ovarian cancer stem cell population." (PMID 21521521, 2011). "In our study, we have observed enriched population of CSCs in MUC4-transfected ovarian cancer cells using Hoechst33342 dye and CD133-positive population analysis." (PMID 21521521, 2011). "In the present study we have analyzed the expression of HER2 in MUC4 overexpressed ovarian cancer cells." (PMID 21521521, 2011). "In this study, we investigated the functional role of MUC4 in the human ovarian cancer cell line SKOV3." (PMID 18665193, 2008). "One of the important observations of this study was the interaction of MUC4 and HER2 in ovarian cancer cells, which was also associated with the potentiation of HER2 downstream signalling." (PMID 18665193, 2008). "Taken together, our findings demonstrate that MUC4 plays a role in ovarian cancer cell motility, in part, by altering actin arrangement and potentiating HER2 downstream signalling in these cells." (PMID 18665193, 2008). "The mucin MUC4 is overexpressed in many epithelial malignancies including ovarian cancer, suggesting a possible role in the pathogenesis of these cancers." (PMID 18665193, 2008). "In this study, we have investigated the functional consequences of ectopic MUC4 expression in a human ovarian cancer cell line SKOV3." (PMID 18665193, 2008). "Overall, our results demonstrate that MUC4 plays a crucial role in regulating the motility of ovarian cancer cells possibly by altering the expression and activation of HER2 and its downstream signalling." (PMID 18665193, 2008). "The Indian Cohort showed MUC16, MUC4, and CIITA to be most mutated and carry CNV in the same genes apart from MYC, which is known to be amplified in most cancers, including ovarian cancer." (PMID 37091785, 2023). "Hence, the frequency and hotspot mutations in the genes NCOR2, CIITA, MUC4, and MUC16 point towards their role in driving oncogenesis in all ovarian cancer histotypes." (PMID 37091785, 2023). "Moreover, overexpression of MUC4 leads to up-regulation of the CD133 stem cell marker either directly or indirectly via HER2 in ovarian cancer." (PMID 32098629, 2020). "Therefore, a reduction in MUC4 expression during the late stage of ovarian cancer indicates a greater likelihood of survival." (PMID 27829225, 2017). "In addition, a previous work of our group have demonstrated that ectopic overexpression of MUC4 in ovarian cancer cells leads to up-regulation of FAK mediated downstream signaling." (PMID 25686822, 2015). "Mucins 4/16 (MUC4/16) are identified as tumor antigens in epithelial ovarian cancer." (PMID 26356073, 2015). "MUC4 is known to be overexpressed in many types of carcinomas, including ovarian carcinoma." (PMID 21521521, 2011). "Hence, the present study showed that MUC4 overexpression is enriching the cancer stem cell population and it is expressed in stem/progenitor cells in ovarian cancer cells." (PMID 21521521, 2011). "Interestingly, the tumor sphere type circular colony formation was observed only in the MUC4 overexpressed ovarian cancer cells." (PMID 21521521, 2011).